CREM (cAMP responsive element modulator)
Diseases named in the same sentence as CREM in open-access papers (continued):
Sharing a sentence is not in itself a finding about the gene and the disease.
Cirrhosis (1 paper, 2014). A chronic disorder of the liver in which liver tissue becomes scarred and is partially replaced by regenerative nodules and fibrotic tissue resulting in loss of liver function. "In human HCC gene expression datasets, CREM was infrequently up-regulated in tumors (although frequently up-regulated in cirrhosis); similarly, CREM DNA was infrequently amplified (10p11.21 region)." (PMID 25401338, 2014).
depression (1 paper, 2020). "In accordance, gene expression changes across brain tissues reveal altered neurotransmitter signaling and cluster in functional pathways associated with depression including ‘Adrenergic-, GPCR-, cAMP-, and CREB/CREM-signaling’." (PMID 32681022, 2020).
diarrheal disease (1 paper, 2025). The condition of having at least three loose or liquid bowel movements each day. "Our results establish common variants in the loci for the transcription factor, CREM, as having a modulatory role simultaneously in both undernutrition and immune protection against diarrheal disease." (PMID 40576353, 2025).
dilated cardiomyopathy (1 paper, 2021). Cardiomyopathy which is characterized by dilation and contractile dysfunction of the left and right ventricles. "LPIN1, PPP1R3C, PTPN1, CREM, and NR0B2 were identified as the main effectors in metabolism dysregulation in the remote zone and were found differentially expressed also in the myocardium of patients with ischemic and/or dilated cardiomyopathy." (PMID 34722683, 2021).
injury (1 paper, 2015). Damage inflicted on the body as the direct or indirect result of an external force, with or without disruption of structural continuity. "We recently showed that in opposite, CREM overexpression in T cells aggravates an LPS-mediated model of acute lung injury, while CREM−/− T cells mediate protection." (PMID 26459392, 2015).
mucoepidermoid carcinoma (1 paper, 2021). A carcinoma morphologically characterized the presence of cuboidal mucous cells, goblet-like mucous cells, squamoid cells, cystic changes, and a fibrotic stromal formation. "With the expression pattern of CREM portrayed, we also test whether CREM IHC could be used as an indicator of the presence of EWSR1-CREM fusion gene in low-grade mucoepidermoid carcinoma (MEC)." (PMID 34261344, 2021).
ovarian tumours (1 paper, 2012). "We next looked for co-expression of CCNY/CREM in our previous analysis of ovarian tumours." (PMID 22514011, 2012).
sarcopenia (1 paper, 2022). Progressive decline in muscle mass due to aging which results in decreased functional capacity of muscles. "In experimental mouse models, CREM expression was associated with preventing inflammation and myofibrillar protein degradation that affect sarcopenia." (PMID 35271662, 2022).
schizophrenia (1 paper, 2018). A major psychotic disorder characterized by abnormalities in the perception or expression of reality. "It was suggested that synaptic genes, including CREB1, CREM, PPP3CB, and PRKAR1A, are involved in the etiology of schizophrenia-related psychiatric disorders and regulated by the cAMP/PKA/CREB signaling pathway." (PMID 30214393, 2018). "However, the interactions of CREB/CREM and CREB/ATF-1 in the pathophysiology of schizophrenia are unknown and will not be further addressed." (PMID 30214393, 2018).
thyroid tumor (1 paper, 2021). A benign or malignant neoplasm affecting the thyroid gland. "This latter observation is in good agreement with the lack of correlation between CREM and DICER1 mRNA levels in human thyroid tumors." (PMID 33176626, 2021).
tumor (28 papers, 2014 to 2025). "Neoplasms with fusions between Ewing sarcoma breakpoint region 1 (EWSR1) or fused in sarcoma (FUS) genes and genes encoding the CREB family of transcription factors (ATF1, CREB1, and cAMP-responsive element modulator [CREM]) are one such tumor type." (PMID 40242428, 2025). "ACTIN::MITF- and MITF::CREM-rearranged tumors are categorized as melanocytomas in the melanocytic tumors chapter while neoplasms with CRTC1::TRIM11 fusions are classified as malignant soft tissue tumors with uncertain differentiation." (PMID 39264472, 2024). "Recently, a group of intra-abdominal FET(EWSR1/FUS)::CREB(CREM/ATF1) fused unclassified neoplasms has been reported followed by recent recognition of an analogous extra-abdominal category of unclassified neoplasms carrying EWSR1::ATF1 fusions." (PMID 39249507, 2024). "Instead, further molecular genetic testing showed that the tumor harbored a rare EWSR1::CREM fusion combined with a previously unreported IRF2::NTRK3 fusion." (PMID 37274229, 2023). "In the immunohistochemical analysis, we found moderate positive CREM staining homogeneously in most tumor cell nuclei in all five cases (80–88% of cells)." (PMID 34261344, 2021). "Recent studies have identified fusion genes, with CREM as a partner gene in many neoplastic diseases." (PMID 34261344, 2021). "In order to further explore the potential reasons for the positive correlation between CREM and tumorigenesis and development, we further investigated the correlation between CREM expression with tumor immune microenvironment." (PMID 34938728, 2021). "Protein expression analyses of the tumor relevant genes CREM GLS2, PER3 and TXNIP mostly showed a diametrical regulation compared to mRNA expression in both cell lines under acidotic conditions." (PMID 33407762, 2021). "Fusions between members of the FET gene family (EWSR1 and FUS) and genes encoding for the CREB-transcription factor family (ATF, CREB1, and CREM) have been reported in a variety of clinically and pathologically distinct neoplasms of mesenchymal, epithelial and mesothelial origin." (PMID 39031200, 2024). "Second, we wanted to examine whether a tumor with an EWSR1-CREM fusion gene might overexpress the fusion protein, resulting in stronger immunohistochemical CREM staining intensity than seen in the corresponding normal tissues." (PMID 34261344, 2021). "Case 13, which had both EWSR1 and CREM rearrangements (metastatic lesions in lymph nodes), showed sheet-like and fascicular proliferation of epithelioid and spindle tumor cells that had round nuclei with conspicuous nucleoli and abundant pale eosinophilic cytoplasm; no myxoid change was found." (PMID 30219084, 2018). "CREM is highly expressed in tumor tissues and may play an important role in GAC." (PMID 34938728, 2021). "Thus, a likely essential function of CREM in M2 macrophages is to mediate immunosuppression, which may be a potential target for tumor immunotherapy, but the mechanistic details need further study." (PMID 33298893, 2020). "Among 12 tumors with known fusion partners, the fusions partner was CREB1 in 6 cases (50%), CREM in 4 tumors (33%), ATF1 in one tumor (8%) and PBX3 (8%) in another tumor." (PMID 40748380, 2025). "In groups A5, A6, A7, and A8, genes such as CXCL13, HSPA1A, CREM, CCL4, and FOS were highly expressed in CD8+ or CD4+ T cells in tumor tissues." (PMID 37762493, 2023). "Our report depicted the important role of CREM in GAC, and revealed the relationship between CREM and tumor-infiltrating lymphocytes in GAC." (PMID 34938728, 2021). "More recently, CREM, has also been identified as a transcriptional checkpoint in natural killer (NK) cells, where its deletion enhances CAR-NK cell anti-tumor efficacy by derepressing key effector genes such as PRF1 and GZMB, implicating this pathway in broader immunoregulatory functions." (PMID 40719625, 2025).
tumor (continued). "Notably, we identified a subset of M2 macrophage with high expression of CCL18 and transcription factor CREM that was enriched in advanced HCC patients, and potentially participated in tumor progression." (PMID 33298893, 2020). "Furthermore, 10 of these 26 (38.5%) patients had a tumor with an EWSR1::ATF1 fusion, eight (30.8%) had EWSR1::CREB1 fusion, six (23.1%) had EWSR1::CREM, one (3.8%) had EWSR1::CREB3L3, and one (3.8%) had FUS::CREM fusion." (PMID 38291529, 2024). "Subsequently, at a pathology consultation, the tumor was found to be negative for MUC4 and SSX (C-term), while FISH analysis detected rearrangements for both EWSR1 and CREM genes." (PMID 40242428, 2025). "We have tested CREM protein expression in 13 human HCC samples of various etiologies, and have found CREM-positive nuclei in 11 HCCs (85%), but not in the non-tumor cirrhotic liver." (PMID 25401338, 2014). "Nevertheless, IHC demonstrated CREM-positive nuclear staining in 11/13 tested human HCC tumors, but not in the surrounding non-tumor liver, independently on the patient's age and gender and on HCC etiology, probably indicating a transcript level-independent mechanism of CREM up-regulation." (PMID 25401338, 2014).
cancer (10 papers, 2014 to 2023). A tumor composed of atypical neoplastic, often pleomorphic cells that invade other tissues. "By GSEA cluster analysis, we found that the high expression of CREM was associated with the cancer-associated pathway in GAC." (PMID 34938728, 2021). "Through KOBAS database and GSEA analysis, we found that the high expression of CREM is closely related to cancer-associated pathways." (PMID 34938728, 2021). "We found that CREM is associated with a variety of cancer-associated pathways, such as focal adhesion, PI3K-Akt signaling pathway, cGMP-PKG signaling, cell adhesion molecules, MAPK signaling pathway, Rap1 signaling pathway, TGF-beta signaling pathway, and Ras signaling pathway." (PMID 34938728, 2021). "When examining the expression of CREM in different cancers, over-expression has been observed in skin and immune cancers, whereas down-regulation is observed in other types of cancers." (PMID 37628737, 2023). "Functionally, these differences in context help to explain the clinical and biological differences in cancers that contain the same driver mutation (e.g., the diverse cancers with mutations in PDE11A or with those with mutations in CREB/ATF/CREM)." (PMID 36313756, 2022). "The difference between CREM mRNA level in normal tissues and cancer was statistically significant in all organs except colon, skin, and stomach." (PMID 34261344, 2021). "Human lines Huh7 and Hep40 were selected for studying the role of CREM in cancer cell proliferation by knockdown experiments using CREM-specific siRNA." (PMID 25401338, 2014). "The prevalence of the EWSR1::CREM fusion gene in cancer has been estimated at 0.05%4." (PMID 36966162, 2023). "A transcriptomic analysis of normal tissues and cancer showed that transcription of CREM can be altered in tumors, suggesting that also wild-type CREM may be involved in cancer biology." (PMID 34261344, 2021). "In transcriptomic analysis, we found that CREM may be clearly upregulated or downregulated in cancer, depending on the tissue type." (PMID 34261344, 2021). "Conversely, in most forms of cancer, downregulation of CREM expression was noted." (PMID 34261344, 2021). "CREM is involved in cancer and circadian regulation of cholesterol synthesis in the liver." (PMID 31057604, 2019). "Next, we studied whether CREM expression is altered in cancer." (PMID 34261344, 2021). "Ideally, the effects of endogenous EWSR1::CREM protein would be studied in a cancer cell line that does not express CREM." (PMID 36966162, 2023).
adenocarcinoma (3 papers, 2013 to 2014). A common cancer characterized by the presence of malignant glandular cells. "The modest roles of CREB and, by implication, CREM and ATF1 in the GI was a genuine surprise, but there was evidence that pCREB/CREM/ATF1 is elevated in early-stage and advanced adenocarcinoma in the mouse." (PMID 23618903, 2013).
infection (3 papers, 2018 to 2025). The state of being infected such as from the introduction of a foreign agent such as serum, vaccine, antigenic substance or organism. "After 72 h, CREM expression was significantly lower in mice that had cleared the infection (both wild type and susceptible) relative to mice that were still infected (Q223R only) (−0.18 ± 0.08; P = 0.031)." (PMID 30228239, 2018). "Individuals with at least one copy of the CA insertion at rs58000832, an intergenic insertion between CREM and CCNY, had 2.42 times increased odds of diarrhea-associated infection within the first year of life compared to individuals with no copies of this insertion." (PMID 30228239, 2018). "The PPI observed that the hub genes with the largest number of associated nodes in the weighted network played a crucial role in the immune cell recruitment and activation after infection, such CXCR1, VNN2, BST1, CREM, IL1R1, and CD48." (PMID 39692191, 2025).
heart disease (1 paper, 2018). "Multiple genes known or plausibly linked to heart development and post-natal heart disease were found to be differentially methylated in the blood DNA of newborns with TOF including: ABCB1, PPP2R5C, TLR1, SELL, SCN3A, CREM, RUNX and LHX9." (PMID 30212560, 2018).
CREM also shares sentences with these, for which no sentence is quoted: clear cell sarcoma (5 papers); clear cell carcinoma (3); epilepsy (3); Obesity (3); soft tissue tumors (3); breast carcinoma (2); COVID-19 (2); heart failure (2); juvenile idiopathic arthritis (2); leukemia (2); liver cancer (2); neurodegenerative disease (2); rheumatoid arthritis (2); acute myeloid leukemia (1); Allergy (1); anaplastic astrocytoma (1); angiomatoid fibrous histiocytoma (1); angiosarcoma (1); Azoospermia (1); cardiac hypertrophy (1); cardiac ischemia (1); cardiovascular disease (1); colon adenocarcinoma (1); colon cancer (1); Crohn disease (1); esophageal carcinoma (1); esophageal squamous cell carcinoma (1); Ewing sarcoma (1); hepatocellular carcinoma (1); hyperlipidemia (1).
A further 23 diseases each share a sentence with CREM in 1 paper.